Y_RNA (Y RNA )
Gene: Miscellaneous RNA gene on chromosome 20 (2,453,010 to 2,453,117, reverse strand). Ensembl gene ENSG00000207305.
Homologues: Orthologues: chimpanzee Y_RNA (97% identical), macaque Y_RNA (92% identical). Paralogues in human: Y_RNA (83% identical), Y_RNA (82% identical), Y_RNA (81% identical), RNY1P5 (81% identical), Y_RNA (80% identical), Y_RNA (79% identical), RNY1 (78% identical), Y_RNA (78% identical), RNY1P2 (77% identical), Y_RNA (77% identical), RNY1P6 (76% identical), Y_RNA (76% identical), and 94 more.